E2F1 (E2F transcription factor 1)
Diseases named in the same sentence as E2F1 in open-access papers (continued):
Sharing a sentence is not in itself a finding about the gene and the disease.
colon carcinoma (continued). "Thus, E2F1 may direct the HR-mediated DNA repair pathway, which is important for maintaining genome stability in human colon cancer cells." (PMID 31534120, 2019). "Thus, the TFs of E2f1, Hsfy2, and Nfyb may play key roles in colon cancer and the functions should be further studied." (PMID 28588641, 2017). "E2f1, Hsfy2, and Nfyb may be therapeutic targets for colon cancer." (PMID 28588641, 2017). "Thus, the combined E2F1/TS immunophenotype could be a potential indicator of colon cancer sensitivity to 5FU." (PMID 26831819, 2016). "In addition, it has been reported that E2F1, 2 and 3 are targets of miR-34a in colon cancer cells." (PMID 25889255, 2015). "Cellular experiments confirmed aspirin downregulated metastasis‐related genes (E2F1, CCNE1, VEGFA, MMP3) in colon cancer." (PMID 41425852, 2025). "E2F1 (logFC(E2F1)=1.757) was indeed highly expressed in COAD, and it has been shown to be involved in the proliferation and apoptosis of colon cancer cells." (PMID 39202109, 2024). "In colon cancer, CDK8 enhances the activity of β-catenin and suppresses the activity of E2F1 (repressor of β-catenin), thereby indirectly promoting the expression of c-myc." (PMID 37446017, 2023). "VMP1-mediated autophagy is induced by gemcitabine through the transcription factor E2F1 in pancreatic cancer cells and by photodynamic therapy through HIF-1α in colon cancer cells." (PMID 37629161, 2023). "miR-192 also benefits the prognosis of colon cancer patients by regulating SRPX2, Rab-2A, RhoA-ROCK-LIMK2, farnesoid X receptor, RB1/E2F1 pathway, and NOD2." (PMID 33614788, 2021). "Transient over-expression of miR-34a in human colon cancer cell lines HCT116 and RKO inhibited proliferation and induced senescence-like phenotypes, and suppression of the transcription factor E2F1." (PMID 31658284, 2019). "In addition to E2F1, elevated levels of HR proteins in colon cancer cells may facilitate HR, fork reversal, and PRR, which is the most efficient pathway for ssDNA gap repair during DNA replication and simultaneously promotes the repair of damaged DNA via a sister template after DNA replication." (PMID 31534120, 2019). "Decreased expression upon KRT23 knockdown was confirmed at the protein level for key molecules MRE11A, E2F1, RAD51 and BRCA1 and knockdown of KRT23 rendered colon cancer cells more sensitive to irradiation." (PMID 24039993, 2013). "It is possible that the negative interaction between p21 and E2F1 was lost in certain colon cancer cells and restored on PXR expression, the mechanism of reduction of E2F1 remains to be investigated." (PMID 20531417, 2010). "Our studies indicated that the deregulation of E2F1, E2F2, E2F3, E2F5, E2F7 and E2F8 in colon cancer tissues might play a vital role in colon cancer oncogenesis, which could be promising diagnostic biomarkers for LUAD." (PMID 32117628, 2020). "To investigate E2F1-mediated regulation of HR gene expression in colon cancers, we analyzed mRNA expression levels in colon cancer cells in the presence or absence of siE2F1 via qPCR." (PMID 31534120, 2019). "Finally, we investigated the intracellular localization of E2F1, RAD51, and replication protein A (RPA) in colon cancer cells exposed to methyl methanesulfonate (MMS), which induces DNA double-strand breaks (DSBs)." (PMID 31534120, 2019). "Our previous report reveals that in HCT116 colon cancer cells, the BIR domains of XIAP could bind E2F1 to promote cell growth by strengthening cyclin E expression." (PMID 31811115, 2019). "We conclude that the E2F1+TS+ immunophenotype may be a marker of poor prognosis (the worst DFS and OS) in patients with colon cancer treated with 5FU-based adjuvant therapy." (PMID 26831819, 2016).
colon carcinoma (continued). "The E2F1+TS+ immunophenotype may be a marker of poor prognosis (the worst DFS and OS) of patients with colon cancer treated with 5FU-based adjuvant therapy." (PMID 26831819, 2016). "Previously, E2F1 was found to be significantly upregulated in colon cancer, however, its levels were not correlated with colon cancer stage and OS, implying that E2F1 may be an important factor in tumorigenesis induction." (PMID 34741389, 2021). "To determine whether colon cancer cells require E2F1 to promote HR activity to induce DNA gap processing and complete DNA replication, we examined the formation of RAD51 foci and RPA foci following the treatment of colon cancer cells with siE2F1." (PMID 31534120, 2019). "Interestingly, KRAS‐mutant colon cancer cells appear to show a greater dependency on PLK1 for survival than KRAS‐mutant lung and pancreatic tumor cells, as single treatment with PLK1 inhibitors (e.g., BI2536) is sufficient to induce high levels of ROS and activation of the p38/JNK/E2F1 axis." (PMID 34369083, 2021). "In our study, we found that the mRNA and protein expression of E2F1 was significantly higher in colon carcinoma, however, the expression level of which did not affect tumor stage and overall survival, suggesting that E2F1 may just serve as a tumor “switch” to induce tumorigenesis." (PMID 32117628, 2020). "Furthermore, E2F1 depletion may have suppressed the HR pathway by interfering with RAD51-mediated DNA recombination and the accumulation of ssDNA gaps, impairing DNA damage repair mechanisms in colon cancer cells." (PMID 31534120, 2019). "Furthermore, E2F1 depletion reduced the formation of RAD51 foci, but not the formation of RPA and γH2AX foci, and the accumulation of ssDNA gaps, indicating that colon cancer cells are able to undergo typical replication processes in the presence of unrepaired ssDNA gaps." (PMID 31534120, 2019).
osteosarcoma (62 papers, 2008 to 2025). A usually aggressive malignant bone-forming mesenchymal neoplasm, predominantly affecting adolescents and young adults. "Previous evidence has demonstrated that lncRNA E2F1-regulated inhibitor of cell death associates with AT-rich interactive domain 3A via E2F1 to promote osteosarcoma progression." (PMID 34408262, 2021). "Meanwhile, E2F1 level has also been found to be associated with poor prognosis of osteosarcoma patients." (PMID 30936265, 2019). "To confirm direct transcriptional regulation of E2F1 on HELLS in human osteosarcoma, we acquired lentiviral vectors encoding shRNAs targeting E2F1 (shE2F1) and transduced the four human osteosarcoma cell lines in which we had previously observed HELLS overexpression." (PMID 30220967, 2018). "For canine osteosarcoma, the G2/M checkpoint was found to be regulated, at least in part, by the retinoblastoma (RB)-E2F1 pathway." (PMID 40386412, 2025). "We performed E2F1 overexpression experiments in U2OS (human osteosarcoma) derived NARF2 cells and HT1080 cells by means of adenovirus." (PMID 36778475, 2023). "The activation of E2F1 in osteosarcoma cells increased endogenous DAPK2 in parallel with cell death." (PMID 36827114, 2023). "Linc00511 can suppress miR-185-3p expression and target E2F1 protein expression, which in turn promotes osteosarcoma cell proliferation and migration." (PMID 35842617, 2022). "It was found that a potential target for miR-320 is the E2F1 gene, regulating the cell cycle of osteosarcoma or fatty acid synthase (FASN) involved in OS metastasis." (PMID 36139691, 2022). "The literature suggests that E2F1 can influence the expressions of EMT-related proteins to induce the advancement of EMT process of osteosarcoma cells." (PMID 35030974, 2022). "E2F1 is identified as a new regulator of osteogenic differentiation of osteosarcoma cells induced by ATRA." (PMID 30936265, 2019). "It was found that E2F1 had a significant regulatory relationship with the three dysfunction modules and was considered as a key regulation molecule in the process of osteosarcoma." (PMID 30936265, 2019). "In line with this idea, recent work in a human osteosarcoma cell line (U2OS) identified NF‐Yb as a direct target of pro‐apoptotic E2F1 (Jiang, Nevins, Shats, & Chi, 2015)." (PMID 29704264, 2018). "Methylation of R111 and R113 modulates the pro-apoptotic responses to E2F1, and Arg-to-Lys mutation of these residues reportedly yields a mutant “E2F1 RDK” protein with increased stability in osteosarcoma cells." (PMID 27903963, 2017). "We also found that upregulation of microRNA-29 targeting MCL1 via virally induced transcriptional factor E2F-1 activation was critical for the enhancement of chemotherapy-induced apoptosis in osteosarcoma cells." (PMID 27356624, 2016). "E2F1 has been reported to stimulate miR-15a/16 cluster expression in osteosarcoma cell line U2OS and lung adenocarcinoma cell line H1299 by binding to the same site of DLEU2 promoter." (PMID 26397135, 2015). "To study this pathway we utilized an osteosarcoma cell line that conditionally expresses a dominant-negative mutant of E2F1 which localizes to the nucleus upon activation with tamoxifen (ER-dnE2F1)." (PMID 24809452, 2014). "Studies using the Saos-2 osteosarcoma cell line show that mir-449 cluster transcription is inducible by the E2F1 transcription factor." (PMID 25416653, 2014).
osteosarcoma (continued). "Similar results were obtained by the ectopic expression of p16 in the U2OS cells (EH1), indicating that p16 sensitizes the osteosarcoma cells to doxorubicin through E2F1." (PMID 21799732, 2011). "To further elucidate this, we have shown that the over-expression of the E2F1 protein enhances spontaneous as well as doxorubicin-induced apoptosis in the osteosarcoma p16-defective U2OS cells." (PMID 21799732, 2011). "In two independent microarray studies, DYRK1A was among the genes upregulated by overexpression of the transcription factor E2F1 in the human U2OS osteosarcoma cell line and in murine NIH3T3 fibroblasts." (PMID 18366763, 2008). "Deletion of the N-terminal region of E2F1 also reduced activation of the ARF promoter by overexpressed E2F1 in human osteosarcoma U-2 OS cells (U-2 OS left graph), indicating that the reduction in transcriptional activity upon loss of the N-terminal region is not specific to HFFs." (PMID 39595534, 2024). "Inhibition of TMPO-AS1, overexpression of miR-329 and inhibition of E2F1 could defeat proliferation and invasiveness of osteosarcoma cells and enhance their apoptosis." (PMID 36467407, 2022). "The mechanism by which E2F1 regulates the balance of proliferation and apoptosis in osteosarcoma cells remains unclear." (PMID 36408174, 2022). "However, knocking down E2F1 alone was insufficient to decrease UHRF1 expression in osteosarcoma cells." (PMID 36068209, 2022). "This screen employed human osteosarcoma cells that express an inducible E2F1." (PMID 34084281, 2021). "In osteosarcomas, studies have shown Api5 to inhibit E2F1 as well as Acinus-mediated apoptosis." (PMID 34385547, 2021). "Knockdown of E2F1 in osteosarcoma cells results in reduced phosphorylation of STAT3." (PMID 33291686, 2020). "While other studies have proposed that an increase in E2F1 expression could mediate the transcriptional repression of MCL-1, we were unable to detect changes in E2F1 protein levels upon flavopiridol treatment in osteosarcoma." (PMID 29805751, 2018). "E2F1 was a well known oncogene that is targeted by miR-29a-3p in osteosarcoma." (PMID 29214011, 2017). "To investigate the underlying mechanism of OBP-301-mediated MCL1 suppression, we determined whether OBP-301 upregulates MCL1-targeted miRNAs (miR-15, miR-16, miR-29) via E2F1 activation in human osteosarcoma cells." (PMID 27356624, 2016). "For example, of the two E2F activation signatures used in our approach, one signature was obtained by inducing E2F1 activity in rat fibroblast cells while the other signature was obtained using an osteosarcoma-derived cell line containing an inducible ER-E2F1 fusion protein." (PMID 19798449, 2009). "Furthermore, although prior studies have shown that E2F regulation of cIAPs and E2F1 directly promotes MAP3K14 gene expression in osteosarcoma cells, we report for the first time that the E2F transcription factors E2F4 and E2F5 play a role in regulating NIK transcription and expression." (PMID 36945490, 2023). "Finally, the inducible osteosarcoma U2OS E2F1-ER cell line was also tested." (PMID 23449538, 2013). "The miR-185-3p/E2F1 axis was regulated by LINC00511 to promote the occurrence and progression of osteosarcoma." (PMID 36816047, 2023).
osteosarcoma (continued). "In osteosarcoma, upregulation of ATF6 and E2F7 during sustained ERS suppressed E2F1 expression, upregulation of E2F7 was dependent on activation of XBP1, and downregulation of E2F1 enhanced Noxa and Puma expression and promoted ER stress-induced apoptosis." (PMID 36551309, 2022). "Together, the results suggest that in osteosarcoma cells under DNA damage, SETD7 is needed for cell cycle arrest through methylation of pRb or E2F-1 or PPP1R12A." (PMID 35326563, 2022). "SETD7 increases E2F-1 stability, but inhibits E2F-1-dependent transcription of TP73 in osteosarcoma cells." (PMID 35326563, 2022). "In osteosarcoma cells, TMPO-AS1/miR-329/E2F1 axis has been acknowledged as an imporatnt regulator of cell proliferation and apoptosis." (PMID 36467407, 2022). "To determine if changes in E2F1 and MCL-1 proteins participate in the reduced viability that we observe in osteosarcoma cell lines following flavopiridol treatment, we analyzed the expression of these proteins." (PMID 29805751, 2018). "This compensatory effect resulted in no change of ferroptotic target genes after E2F1 knock down in an osteosarcoma cell line." (PMID 36778475, 2023). "SETD7 methylates E2F-1 at K185 stabilising it to enhance the transcription of pro-apoptotic target genes, BIM1 and TP73, suggesting that SETD7 activity inhibits cell growth and enhances the E2F-1 pro-apoptotic effect in osteosarcoma cells." (PMID 35326563, 2022). "Similar result was also observed in the human osteosarcoma cell line, Saos-2, where ectopic expression of Api5 decreased E2F1-mediated apoptosis in E2F1 over-expressing cells without affecting its transcriptional activity." (PMID 34385547, 2021). "LncRNA E2F1-regulated Inhibitor of Cell Death (ERICD) can interact with AT-rich interaction domain 3A (ARID3A) via the E2F transcription factor 1 (E2F1) so as to regulate the proliferation and migration of osteosarcoma cells." (PMID 34373436, 2021). "And there were 38 endogenous genes (including ARF1, HSP90AB1, and TUBA1B), 53 TFs (including E2F1, NFKB1, and EGR1), and 858 ncRNAs (including MALAT1, miR-590-3p, and TUG1) were considered as key regulators of osteosarcoma through a series of function enrichment analysis and network analysis." (PMID 30936265, 2019). "The present study demonstrated that a tumor-specific replication-competent oncolytic adenovirus OBP-301 induced miR-29 upregulation via E2F1 activation, which resulted in suppression of anti-apoptotic BCL2 family protein MCL1 in chemotherapy-resistant human osteosarcoma cells." (PMID 27356624, 2016). "This is intriguing in that the inducible E2F1 system used in this study comes from an osteosarcoma, indicating that the NFYB-dependent E2F1 transcriptional program defined here might be tissue-specific." (PMID 26039627, 2015). "Among these we analyzed CD133, N-Myc, CCND2, E2F1 and E2F2, Bcl-2 and IAP-2, since they are overexpressed in 3AB-OS cells and many of them were found to be frequently overexpressed in tissues of osteosarcoma patients." (PMID 25174983, 2014). "Interestingly, we found that E2F1 knockdown was not effective at reducing HELLS protein levels in any of the osteosarcoma cell lines used." (PMID 30220967, 2018). "We tested compensation by other activator E2Fs and found that knocking down E2F1 alongside E2F3, but not E2F2, reduced UHRF1 expression in osteosarcoma." (PMID 36068209, 2022). "However, some cell lines, including the osteosarcoma cell line HOS, showed reduced colony-formation ability without affecting both c-Myc and E2F1 proteins." (PMID 38141761, 2024). "However, in osteosarcoma cell line HOS, SET knock-down (KD) suppresses the colony-formation ability without affecting c-Myc and E2F1." (PMID 38141761, 2024).